RN7SL487P (RNA, 7SL, cytoplasmic 487, pseudogene)
Gene: Miscellaneous RNA gene on chromosome 15 (43,391,384 to 43,391,727, reverse strand). Ensembl gene ENSG00000243871.
Homologues: Orthologues: chimpanzee Metazoa_SRP (99% identical), macaque Metazoa_SRP (89% identical). Paralogues in human: RN7SL33P (73% identical), RN7SL1 (69% identical), RN7SL40P (69% identical), RN7SL775P (69% identical), RN7SL2 (69% identical), RN7SL3 (68% identical), RN7SL317P (68% identical), RN7SL526P (68% identical), Metazoa_SRP (67% identical), RN7SL5P (67% identical), RN7SL664P (66% identical), RN7SL712P (66% identical), and 699 more.